SMIM10L1 (small integral membrane protein 10 like 1)
Tractability: PROTAC: its protein half-life has been measured.
Gene: Protein-coding gene on chromosome 12 (11,171,194 to 11,176,016, forward strand). Ensembl gene ENSG00000256537.
Gene Ontology:
Cellular component: mitochondrion
Genetic constraint (gnomAD): Loss-of-function variants: 6 observed, 3.31 expected, observed/expected ratio (o/e) 1.81, 90% interval 0.85 to 1.95. That is too few expected variants to judge how well the gene tolerates losing a copy. Missense variants: 66 observed, 63.01 expected, observed/expected ratio (o/e) 1.05, 90% interval 0.86 to 1.29. Synonymous variants: 49 observed, 32.85 expected, observed/expected ratio (o/e) 1.49, 90% interval 1.18 to 1.85.
Homologues: Orthologues: chimpanzee SMIM10L1 (100% identical), rabbit SMIM10L1 (96% identical), guinea pig SMIM10L1 (91% identical), mouse Smim10l1 (85% identical), dog SMIM10L1 (84% identical), rat Smim10l1 (81% identical), pig SMIM10L1 (79% identical), zebrafish smim10l3 (53% identical). Paralogues in human: SMIM10L2A (69% identical), SMIM10L2B (69% identical), SMIM10L3 (66% identical), SMIM10 (63% identical).